LUM (lumican)
Diseases named in the same sentence as LUM in open-access papers (continued):
Sharing a sentence is not in itself a finding about the gene and the disease.
colon carcinoma (16 papers, 2013 to 2024). "Although a few studies have maintained that LUM is associated with unfavorable colon cancer progression, its potential functions and regulatory network in COAD has not been analyzed." (PMID 33493133, 2021). "For example, in gastric and colon cancer, lumican expression was associated with cancer dissemination to secondary sites, lymphatic metastasis, and a poor overall survival of patients." (PMID 34572532, 2021). "The glycoproteins versican and lumican are overexpressed at the mRNA level in colon carcinomas compared to adenomas, and are associated with the formation of tumor stroma." (PMID 28481899, 2017). "The glycoproteins versican and lumican are overexpressed in colon carcinomas and are associated with the formation of tumor stroma." (PMID 22711178, 2013). "The results presented here emphasize that both versican and lumican are associated with colon cancer prognosis." (PMID 22711178, 2013). "Moreover, in colon cancer, liver cancer, neuroblastoma, osteosarcoma, and chondrosarcoma among others, overexpressed LUM has been associated with worse clinical outcomes." (PMID 37692065, 2023). "LUM was shown to be down-regulated upon KLF4 overexpression in a transfected colon cancer cell line." (PMID 38830769, 2024). "With regards to immune responses, LUM is involved in immune escape in the colon cancer microenvironment." (PMID 37692065, 2023). "To understand the role of LUM in the colon cancer microenvironment, we analyzed the co-expression network of LUM in the LinkedOmics website." (PMID 33493133, 2021). "In colon cancer, the lumican expression was correlated with lymph node metastasis and a lower survival rate." (PMID 34572532, 2021). "Overexpression of lumican in human colon cancer cells increased its secretion and enhanced the migration ability of cancer cells through remodeling the rearrangement of actin cytoskeleton and the localization of gelsolin in cytoplasm." (PMID 31963522, 2020). "Overexpression of lumican in colon cancer cells enhanced the cell motility through modulating the rearrangement of the actin cytoskeleton, and another study showed that lumican induced the migration of corneal epithelial cell via the ERK1/2 signaling pathway." (PMID 31963522, 2020). "Lumican is known to be expressed in several cancer types including breast, pancreatic, and colon cancers." (PMID 31963522, 2020). "A previous study showed that overexpression of lumican enhanced the migration of colon cancer cells through modulating the organization of actin filaments, which supports our results in this study." (PMID 31963522, 2020). "In colon cancer, LUM triggers cytoskeletal remodeling and elevates the cellular migration capacity, and, in bladder cancer, LUM expression promotes cell proliferation and migration." (PMID 31861249, 2019). "In colon cancer cells, the overexpression of LUM leads to actin cytoskeletal remodeling and an increased migration capacity." (PMID 31861249, 2019). "Previously, we showed that versican and lumican protein expression are associated to a longer survival of stage II and III colon cancer patients, respectively." (PMID 28481899, 2017). "Overexpression of lumican has also been shown to affect the migration of human colon cancer cells through up regulation of gelsolin and filamentous actin reorganization." (PMID 26930497, 2016). "Lumican was also localized in epithelial cells with mild reactive dysplasia and fibroblasts adjacent to colon cancer cells." (PMID 26930497, 2016). "Indeed, it was determined that lumican facilitated colon cancer progression through a miRNA200-dependent epithelial-to-mesenchymal progression." (PMID 34572532, 2021). "Moreover, in colon cancer, the expression of lumican was positively correlated with the disease stage." (PMID 34572532, 2021). "The motility of colon cancer cells is also upregulated by lumican." (PMID 34572532, 2021).
colon carcinoma (continued). "Functional experiments in vitro confirmed that LUM could enhance the migration of colon cancer cells." (PMID 33493133, 2021). "On the other hand, the protein expression of versican and lumican predicted good clinical outcomes for stage III and II colon cancer patients, respectively." (PMID 31531098, 2019). "Furthermore, lumican secreted into cell culture medium may facilitate colon cancer cell migration." (PMID 28481899, 2017). "The aim of the present study was to investigate the potential prognostic value of versican and lumican expression in the epithelial and stromal compartment of Union for International Cancer Control (UICC) stage II and III colon cancer." (PMID 22711178, 2013). "Protein expression of versican and lumican predicted good clinical outcome for stage III and II colon cancer patients, respectively." (PMID 22711178, 2013). "In combination with MSI status, versican and lumican are putative prognostic biomarkers that predict good outcome in stage II and III colon cancer patients, and in the latter also with respect to the effect of adjuvant chemotherapy." (PMID 22711178, 2013). "The aim of the present study was to investigate the potential prognostic value of lumican and versican expression in the epithelial and stromal compartment of stage II and III colon cancer." (PMID 22711178, 2013). "Furthermore, the expression of lumican is increased during colorectal adenoma-to-carcinoma progression and able to predict good clinical outcomes for stage II and III colon cancer." (PMID 34502094, 2021).
colorectal cancer (13 papers, 2010 to 2024). A primary or metastatic malignant neoplasm that affects the colon or rectum. "In accordance with our results, a previous study showed that a high LUM expression was associated with a significantly reduced survival rate in advanced colorectal cancer with nodal metastasis." (PMID 34590603, 2021). "In advanced colorectal cancer, LUM expression was observed only in cancer cells and was correlated with metastasis in lymph nodes, the depth of tumour invasion and significantly lower survival rates." (PMID 29088800, 2017). "LUM expression in advanced colorectal cancer with nodal metastasis was detected in 62.7% of patients and was correlated with the spread of lymph node metastasis, the depth of tumour invasion and significantly lower survival rates of patients." (PMID 29088800, 2017). "Lumican plays an important role in collagen fibrillogenesis and its over-expression has been reported in human colorectal cancer." (PMID 20459814, 2010). "In addition, colorectal cancer patients with a high expression level of lumican had poor prognosis as compared to those with a low expression level of lumican." (PMID 31963522, 2020). "In approximately 63% of colorectal cancer patients, lumican is up regulated." (PMID 26930497, 2016). "Lumican, another member of the SLRP family, was localized in the cytosol of lung as well as colorectal cancer cells." (PMID 24499526, 2013).
heart failure (13 papers, 2018 to 2025). Inability of the heart to pump blood at an adequate rate to meet tissue metabolic requirements. "The ectopic expression of LUM has been widely demonstrated to be associated with pathological processes, such as cardiac fibrosis, cardiomyocyte hypertrophy, and heart failure as well as in VMSCs with chronic renal failure." (PMID 37711155, 2023). "It has previously shown that LUM levels are increased in hearts of mice and patients with heart failure, via mediation cardiac remodeling, fibrosis, and inflammation, and accumulates with collagen fibers during HCM." (PMID 40843168, 2025). "Our observations revealed that lumican is significantly downregulated in patients with gout and upregulated in patients with heart failure and in MI mice." (PMID 39482719, 2024). "Lumican expression increases during heart failure and cardiac fibrosis, and the stimulation of lumican was shown to further increase cardiac fibrosis." (PMID 39451203, 2024). "When heart failure occurs, fibroblasts produce large amounts of LUM, which is involved in cardiac remodelling processes induced by mechanical and proinflammatory stimulation." (PMID 36863704, 2023). "On the one hand, experimental and clinical findings revealed that the overexpression of lumican in cardiac fibroblasts is evoked during heart failure." (PMID 33716957, 2021). "FMOD and LUM, for example, are increased in heart failure as a response to inflammation and play a role in cardiac remodeling." (PMID 32670412, 2020). "Additionally, lumican expression was markedly elevated in patients with heart failure and in MI mice." (PMID 39482719, 2024). "Our networks succinctly illustrate the most influential nodes in both types of heart failure; for example, in ICM myocardium, a cluster of ECM proteins such as EFEMP1, LUM, and COL6A2 are highly influential, as is TF in the coagulation cascade." (PMID 32487995, 2020). "We screened for differentially expressed genes in heart failure using available gene expression data from the Gene Expression Omnibus database and identified 6 important genes by a random forest classifier (ASPN, MXRA5, LUM, GLUL, CNN1, and SERPINA3)." (PMID 36254001, 2022). "Lack of LUM reduced survival, altered hypertrophic remodeling, increased contractile dysfunction, LV dilatation and lung weight, all pivotal processes in the progression to heart failure." (PMID 31235849, 2019).
Hepatic fibrosis (13 papers, 2011 to 2025). The presence of excessive fibrous connective tissue in the liver. "In a rodent model of carbon tetrachloride-induced hepatic fibrosis, lumican deficiency protected against hepatic fibrosis." (PMID 37960230, 2023). "LUM is a novel essential factor in hepatic fibrosis and encodes an extracellular matrix proteoglycan." (PMID 38224712, 2023). "In addition, lumican has been implicated in hepatic fibrosis." (PMID 37960230, 2023). "We further evaluated Lumican expression, an extracellular matrix proteoglycan that contributes to liver fibrosis by maintaining collagen fibril stability." (PMID 40332584, 2025). "A study on liver fibrosis demonstrated that lumican can be upregulated by the profibrotic cytokine TGF-β1 and lipotoxic PA." (PMID 38774257, 2024). "Lumican was found to increase the expression of collagen in cardiac fibroblasts and to have an important role in hepatic fibrosis." (PMID 36059026, 2022). "Lumican‐null mice have a significantly less severe extent of hepatic fibrosis and significantly higher protein level of α‐SMA and MMP‐13." (PMID 32910552, 2020). "In liver fibrosis, for example, published work has shown that both versican and lumican are regulators of fibrogenesis, but they have opposite effects on collagen reorganization." (PMID 33149218, 2020). "Several lines of evidence suggest that lumican is involved in the pathogenesis of several fibrotic diseases, such as myocardial fibrosis, hepatic fibrosis, corneal collagen fibrillogenesis and pulmonary fibrosis." (PMID 32910552, 2020). "Lumican, a small leucine-rich proteoglycan known to play a role in collagen fibrillogenesis and the development of hepatic fibrosis, was an exception, with FSRs in plasma ranging from 1–3% per day." (PMID 25909381, 2015). "Lumican double‐knockout mice have markedly reduced the extent of hepatic fibrosis." (PMID 32910552, 2020). "Lumican expression is also increased with progression of hepatic fibrosis in rats." (PMID 21526182, 2011). "Decreased sulforylation of lumican side chains stimulates macrophage adhesion and the cellular inflammatory response, suggesting that changes in the structure of lumican may promote the inflammatory process that precedes and enhances collagen deposition during the process of hepatic fibrosis." (PMID 21526182, 2011). "Since the formation of hepatic fibrosis is a complex process of multi-factor and multi-cell involvement, our findings also point to the possible involvement of VACN, COL1A1, COL1A2, LUM, and FBLN5 in the generation of fibrotic response from NAFL to NASH." (PMID 36329886, 2022). "Lumican and TGFBI have previously been reported as tissue markers of liver fibrosis." (PMID 25909381, 2015).
ovarian carcinoma (13 papers, 2011 to 2024). A malignant neoplasm originating from the surface ovarian epithelium. "LUM expression was detected in cytostatic-resistant ovarian cancer cell lines, where this protein was implicated in the collagen fiber assembly." (PMID 39685635, 2024). "We could not confirm the associations of SNPs in two stromal genes,DCN and LUM, with the risk of serousepithelial ovarian cancer, the most common histological type of ovarian cancer,using a multi-stage replication approach within the OCAC." (PMID 21637745, 2011). "Ovarian cancer patients with higher RNA levels of TPH2, DCN, TRHDE, and LUM have lower OS when compared with ovarian cancer patients with lower levels of these genes." (PMID 35008958, 2022). "Overall, the present report is the first to highlight the major role of lumican in the maintenance of the extracellular matrix integrity in the context of ovarian cancer, showing its inhibitory role in primary ovarian tumor allografts growth." (PMID 34885059, 2021). "The aim of this study was to analyze the effect of lumican on tumor growth of murine ovarian epithelial cancer." (PMID 34885059, 2021). "The results demonstrated that lumican inhibited the growth of ovarian cancer mainly by altering collagen fibrilogenesis." (PMID 34885059, 2021). "Our results demonstrate that lumican inhibits ovarian cancer growth mainly by altering collagen fibrilogenesis." (PMID 34885059, 2021). "Lumican was identified in human ovarian cancer ascites, where it was more abundant, as compared to serum control samples." (PMID 34885059, 2021). "The significance of LUM expression in cancer cell drug resistance and cancer development requires further investigation and should be confirmed in other ovarian cancer cell lines, a large cohort of clinical specimens and in animal studies." (PMID 29088800, 2017). "Because LUM expression seems to be related to the progression of different cancers, we decided to investigate its expression in drug-resistant ovarian cancer cell lines in more detail." (PMID 29088800, 2017). "Research performed on a small group of ovarian cancer patients showed different patterns of LUM protein expression according to the type of cancer." (PMID 29088800, 2017). "Expression in ovarian cancer tissue suggests that LUM can play a role in ovarian cancer pathogenesis in ways similar to other cancers." (PMID 29088800, 2017). "The aim of the present study is to determine the expression of LUM in drug-resistant ovarian cancer cell lines." (PMID 29088800, 2017). "In summary, our results present the expression of LUM at the mRNA and protein levels in drug-resistant ovarian cancer cell lines and their corresponding media." (PMID 29088800, 2017). "Our previous microarray results indicated that LUM was overexpressed in three of six drug-resistant ovarian cancer cell lines." (PMID 29088800, 2017). "To gain a better understanding of the role of LUM in drug resistance development, we used an ovarian cancer model, which is the most lethal gynaecological malignancy." (PMID 29088800, 2017). "Theexpression of both decorin and lumican is altered in various cancers, includingserous epithelial ovarian cancer." (PMID 21637745, 2011). "This process might likely be involved in lumican-mediated ECM alteration in the context of ovarian cancer." (PMID 34885059, 2021). "The expression of lumican in cytostatic-resistant ovarian cancer tissue suggests that it might also have a role in drug resistance." (PMID 34885059, 2021). "We analysed distinct types of ovarian cancer in which we could observe different expression levels of the LUM protein." (PMID 29088800, 2017). "Detection of LUM in ovarian cancer tissue confirms its role in cancer pathogenesis." (PMID 29088800, 2017). "Immunohistochemical analysis of the LUM protein was performed in ovarian cancer patients." (PMID 29088800, 2017).
ovarian carcinoma (continued). "Furthermore, previous proteomic profiling of ovarian cancer ascites identified several proteins relevant in this context, including multiple collagens and lumican." (PMID 27659538, 2016). "Finally, we detected the LUM protein in ovarian cancer tissue." (PMID 29088800, 2017). "Following RBPMS knockout, the expression levels of TPH2, DCN, TRHD2, LUM, and SERPINE1 were in agreement with the survival outcomes: The PFS and OS were worse in ovarian cancer patients with higher levels of these transcripts." (PMID 35008958, 2022). "HMGA2 represses the expression of E-cadherin in endometrial carcinoma cells and is inversely correlated with the expression of tumor suppressor lumican (LUM), an inhibitor of EMT, in ovarian cancer." (PMID 26356073, 2015). "Since we previously observed that COL3A1, LUM and MYOT (under review) are secreted to cell culture media in drug resistant ovarian cancer cell lines, we were interested whether MGP can also be present in the culture medium." (PMID 30257426, 2018). "Interestingly, according to the expression profiling based on the parabiosis model of ovarian cancer hematogenous metastasis, four genes (POSTN, LUM, COL3A1, COL5A2) of the LMGS were shown to be significantly up-regulated in the omental metastases generated through a hematogenous route." (PMID 31888563, 2019).
osteosarcoma (12 papers, 2010 to 2024). A usually aggressive malignant bone-forming mesenchymal neoplasm, predominantly affecting adolescents and young adults. "Specifically, we observed that chemotherapy resulted in a subpopulation of osteosarcoma (OS) cells with upregulated expression of genes encoding secreted factors, such as SPP1 and LUM, as well as a distinct population of malignant OS cells." (PMID 39033089, 2024). "Lumican expression was also shown to be positively correlated with the differentiation of osteosarcoma." (PMID 34638415, 2021). "Lumican was also reported to decrease cell proliferation in osteosarcoma, to inhibit cell invasion in prostate cancer and in breast cancer." (PMID 34638415, 2021). "At the same time, TGF-β2, which is involved in growth suppression and cell adhesion in osteosarcoma, and is negatively regulated by lumican, has been highly expressed in SMM." (PMID 33917061, 2021). "In the case of module 3 genes associated with osteosarcoma, eight are found in COSMIC (LUM, COL6A3, TNC, CALU, COL16A1, OMD, ITGB5, and DPSYL3), and two (CDH11 and OMD) are oncogenes found in OncoKB." (PMID 34570764, 2021). "One more mechanistic approach, including an in-/out-signalling cascade, was reported concerning lumican, secreted by human osteosarcoma cell lines." (PMID 28332606, 2017). "LUM, or lumican, may be positively correlated with the differentiation and negatively correlated with the progression of osteosarcoma." (PMID 37681913, 2023). "Likewise, lumican expression and secretion by osteosarcoma Saos-2 and MG63 cells are correlated with their differentiation." (PMID 34572532, 2021). "In contrast, lumican was reported to decrease cell proliferation in osteosarcoma." (PMID 32548117, 2020). "TNC, LUM, COL12A1, COL6A3, and BGN are among the DEPs that differentiate the chondroblastic group from other subtypes of osteosarcoma." (PMID 37681913, 2023). "Lumican was also found to be an endogenous inhibitor of TGF-β2 activity, resulting in downstream effector modulation, including pSmad 2, integrin β1, and pFAK, to regulate osteosarcoma adhesion." (PMID 37681913, 2023).